APOE (apolipoprotein E)
Diseases named in the same sentence as APOE in open-access papers (continued):
Sharing a sentence is not in itself a finding about the gene and the disease.
dementia (continued). "Moreover, there was a significant interaction between PPI use and APOE ε4 genotype for dementia, and the association was most prominent in APOE ε4 heterozygotes." (PMID 36045363, 2022). "Rasmussen and colleagues examined a comprehensive list of cardiovascular risk factors and genetic risk in relation to dementia and showed the highest 10-year absolute risk of all-cause dementia in individuals who smoked with diabetes, low education, APOE ε4, and 22–31 GWAS risk alleles." (PMID 35711612, 2022). "The role of apoE as an upstream mediator in complex pathways underlying neurodegeneration and cognitive decline makes it an ideal therapeutic target for AD and related dementias." (PMID 36348357, 2022). "On the other hand, the E4 allele for APOE increased the risk of dementia and peripheral neuropathy." (PMID 35733470, 2022). "Apolipoprotein E is positively correlated with headache, which may explain why females with a history of headaches have a slightly higher risk of dementia than males." (PMID 35221992, 2022). "Interestingly, low plasma apoE levels have been linked to lower hippocampal size, cognitive impairment, and an increased risk of AD and other types of dementia." (PMID 36002891, 2022). "For instance, low plasmatic levels of apoE are related to a higher risk of developing dementia." (PMID 36153580, 2022). "APOE ε4 allele status in Korean dementia patients with severe white matter hyperintensities." (PMID 35197840, 2022). "In addition, apolipoprotein E (APOE) ε4 allele, as a well-established genetic risk factor for dementia, has been associated with a short sleep duration." (PMID 34979998, 2022). "In addition, the associations of sleep problems with dementia and AD were evident mainly among young-old adults (age 65-74 years) and APOE ε4 allele carriers." (PMID 34979998, 2022). "Possible mechanisms for the potential association between PPIs and dementia and whether PPIs can interact with APOE require evidence from population-based studies." (PMID 36045363, 2022). "Therefore, sleep disorder itself seems to jeopardize dementia risk more than the ApoE genotype does." (PMID 36578446, 2022). "We unprecedentedly reported the interaction between PPI use and APOE ε4 genotype in dementia risk." (PMID 36045363, 2022). "Male sex became statistically significantly associated with all-cause dementia incidence while age, physical activity (inversely), depression with current pharmacotherapy, and the APOE genotypes ɛ2/ɛ4, ɛ3/ɛ4, and ɛ4/ɛ4 remained significantly associated with all-cause dementia incidence." (PMID 36085081, 2022). "Taken together, whether the association of sleep characteristics with dementia varies by demographics (age, sex, and education) and APOE genotype remains unclear." (PMID 34979998, 2022). "However, we analyzed the association between carotene/polyunsaturated fatty acid/vitamin C and incident dementia adjusting for age, sex, education years, and APOE, and found that higher vitamin C intake was associated with lower dementia risk." (PMID 36505244, 2022). "Carrying a higher number of APOE ε4 alleles was associated with greater risk of dementia (HR 1.98 [95% CI 1.73–2.27]), lower cognitive function z–score (‐0.08 [‐0.12 to ‐0.05]), and greater weight loss between baseline and follow‐up (‐0.40 [‐0.62 to ‐0.18] kg weight change per ε4 allele)." (PMID 36092692, 2022). "In addition, the association between proton pump inhibitor use and all-cause dementia differed by APOE genotype (P for interaction = 0.048)." (PMID 36045363, 2022). "Note that each one-year increase in BioAge1 and BioAge2 was associated with 3% (HR 1.03; 95%CI 1.00–1.06; p = 0.08) and 5% (HR 1.05; 95%CI 1.02–1.08; p = 0.001) elevated risk of dementia, respectively, after adjusting for chronological age, APOE status and gender." (PMID 34354164, 2021). "Low education might thus be inflating dementia risk among people with the high-risk variant of the APOE e4 gene." (PMID 34366944, 2021).
dementia (continued). "Interestingly, both NAFLD and dementia share two important biological risk factors, such as Apolipoprotein E (APO-E) and Adiponectin (ADPN)." (PMID 34955810, 2021). "Likewise, their risk of dementia is increased if they carry an APOE ε4 allele or other known genetic risk factor and/or if they have a strong family history of the disease." (PMID 34504080, 2021). "In addition, participants with one and two APOE ε4 alleles had two- and seven-fold increased odds of all-cause dementia compared with participants with two ε3 alleles." (PMID 32404947, 2021). "Apolipoprotein E (apoE) was frequently linked to dementia progression in general, but in COVID-19, this factor may be of particular importance." (PMID 34944606, 2021). "However, we cannot exclude other physiological processes, such as factors related to the patient’s lineage (e.g., apolipoprotein E [ApoE] status) or a vascular disease causing both HL and dementia." (PMID 33627087, 2021). "Whether the effect of lifestyle on cognition varies by genetic dementia risk represented by different APOE genotypes is still unclear." (PMID 34061824, 2021). "Interestingly, subsample analyses of the FINGER and MAPT studies showed that interventions were more effective in patients at increased risk for dementia based on genetic (APOE ɛ4) or biological (amyloid positivity) risk factors." (PMID 34635163, 2021). "However, there was a significant interaction between a composite of lifestyle and health factors and APOE/polygenic risk in relation to all-cause dementia in the Rotterdam Study." (PMID 34635138, 2021). "Furthermore, evidence suggests that both NAFLD and dementia share two important biological risk factors, such as Apolipoprotein E (APO-E) and Adiponectin (ADPN)." (PMID 34955810, 2021). "Our interpretation of the data is that the APOE e4 allele may contribute to the development of dementia, but the association between the e4 allele and the delayed recall test is also seen in the SCD and MCI groups." (PMID 34194377, 2021). "In addition to AD, APOE ε4 plays a role in other causes of dementia, including vascular dementia, and Lewy Body disease." (PMID 33397450, 2021). "Lower risk of developing dementia among ApoE 2 allele carriers." (PMID 34183988, 2021). "However, none of these studies investigated the effect of AD‐PRSs and the possible interaction with APOE genotypes on dementia risk in very old individuals." (PMID 33532541, 2021). "Furthermore, microglia in post-mortem AD brains exhibit accelerated aging and transcriptional alterations associated with the isoforms of ApoE, a protein broadly related to both dementia and cardiovascular disease." (PMID 34566627, 2021). "In the current study, the inclusion of older participants renders a selection of healthier APOE ɛ4 carriers who may carry additional genetic variants preventing them from developing dementia at the ages observed." (PMID 33532541, 2021). "APOE genotype modified the association between smoking and dementia risk." (PMID 34155245, 2021). "In this study, we comprehensively evaluated APOE ε4's association with dementia by race and sex." (PMID 34744974, 2021). "Researchers found that APOE as well as other common genetic variants could have a cumulative risk on the progression of dementia and AD as age advances." (PMID 35368830, 2021). "Apolipoprotein E (APOE) is a lipid-carrier protein tightly linked to dementia." (PMID 33841127, 2021). "The ε4 allele of the apolipoprotein E (APOE ε4) gene is the strongest known genetic risk factor for dementia and cognitive impairment, and it may represent roughly half of the genetic risk for neuropathologically based cognitive diseases." (PMID 34616288, 2021). "Several studies have shown that SCD may be associated with risk factors for dementia, such as the apolipoprotein E (APOE) ε4 allele and the neuropathology of AD." (PMID 33603659, 2021).
dementia (continued). "Across age groups, APOE ε4 carriers are considered to be at greater risk of developing β-amyloid neuropathology as well as clinical dementia, while APOE ε2 carriers are protected against dementia by mechanisms that are generally unknown." (PMID 33786000, 2021). "We used joint models to examine the association of APOE genotype with cognitive function trajectories between 45 and 85 years taking drop-out, dementia, and death into account and Fine and Gray models to examine associations with dementia." (PMID 33397450, 2021). "Further, APOE ɛ4 was associated with increased risk of dementia (1.60, 1.35–1.92, P = 1 × 10–7)." (PMID 33532541, 2021). "Moreover, physical frailty accelerates cognitive decline among ApoE ε4 allele carriers, but cognitive and physical activities slow the onset of dementia and reduce brain pathology." (PMID 34647905, 2021). "The ε4 allele of Apolipoprotein E (APOE4) is the strongest known genetic risk factor of late-onset AD, but only 7% of dementia cases are attributable to APOE4, suggesting that additional genetic or environmental factors are of high relevance in AD pathogenesis." (PMID 32404947, 2021). "However, apart from the link with dementia, the association between APOE ε4 and change in cognition over the adult lifespan is uncertain." (PMID 34205498, 2021). "Apolipoprotein E (APOE) status may modify the threshold for associations between physical exercise and dementia." (PMID 34276532, 2021). "APOE genotype acts in conjunction with other genetic and/or environmental factors to confer AD risk: the lifetime risk of dementia or mild cognitive impairment is 31%–40% for ε4/ε4 homozygotes but the effects of APOE ε4 have been shown to be modified by ethnic background and sex." (PMID 33397400, 2021). "We evaluated whether the association between cigarette smoking and dementia risk is modified by genetic predisposition including apolipoprotein E (APOE) genotype and polygenic risk (excluding the APOE region)." (PMID 34155245, 2021). "Moreover, APOE ɛ2 carriership was associated with reduced risk of dementia (HR 0.69; 95% CI 0.51–0.95, P = .02)." (PMID 33532541, 2021). "Although it is still unclear whether APOE4 raises dementia risk by a gain of toxic function and/or loss of protective function, APOE-based therapies might address both mechanisms at local and systemic levels." (PMID 33841127, 2021). "In the sensitivity analyses of the 82 patients with p.Arg544Cys mutation, SBP, and APOE ε4 genotype remained significant for increased risk of incident stroke (HR 1.49; 95% CI 1.08–2.06; p = 0.016) and dementia (HR 10.97; 95% CI 1.41–85.61; p = 0.022) in adjusted analyses." (PMID 33328970, 2020). "The genetic predisposition of TGA is unknown; however, it is recognised that APOE e4 is a risk factor for dementia." (PMID 32143587, 2020). "Similarly, in this study, active jobs appeared to nullify the detrimental effect of genetic predisposition, as the risk of dementia among APOE ɛ4 carriers with active jobs was similar to that of the non-APOE ɛ4 carriers with active jobs." (PMID 32081835, 2020). "Genetic (APOE: AUC = 0.857) and brain volume variables (total brain tissue volume: AUC = 0.858, hippocampal volume: AUC = 0.857) were also strongly associated with incident dementia." (PMID 32925047, 2020). "Besides, the associations with the APOE have been observed in several other central nervous system diseases, such as dementia with Lewy bodies, recovery of stroke, and risk of cognitive impairment after chemotherapy." (PMID 33328970, 2020). "Future studies should examine whether APOE ε4, in combination with entorhinal-mediated disorientation, predicts dementia risk or prodromal onset in mid to late life adults." (PMID 32960930, 2020). "The potential role of APOE genotype in modulating the risk of dementia with increased alcohol consumption remains unclear with studies pointing in both directions." (PMID 33050383, 2020).
dementia (continued). "The presence of the apolipoprotein E gene (APOE‐ε4) was associated with an earlier dementia onset by approximately 24.9 months, whereas intermediate and low levels of wealth were associated with an accelerated time to dementia diagnosis by 12.0 months and 18.7 months, respectively." (PMID 32187654, 2020). "In the current study, we found that passive jobs increased the risk of dementia due to APOE ɛ4." (PMID 32081835, 2020). "ApoE subspecies had similar associations with AD as with all-cause dementia." (PMID 32648923, 2020). "Notably, amyloid deposition in subjects with SCD is also affected by other risk factors for dementia due to AD, such as the ApoE ɛ4 genotype and age." (PMID 32962744, 2020). "Among those contacted for participation, enrolment was higher for individuals who were younger, more educated, or males or had a family history of dementia, while amyloid positivity in the trial-ready cohort was only associated with being older and carrying an APOE ɛ4 allele." (PMID 31907067, 2020). "Moreover, APOE‐ε4 was associated with an accelerated time to dementia diagnosis by approximately 24.9 months and 33.9 months for clinical AD dementia diagnosis." (PMID 32187654, 2020). "Moreover, aging, APOE ɛ4 allele, risk alleles in genome-wide association studies (GWAS), and cardiovascular risks increased the 10-year absolute risk of all-cause dementia." (PMID 33352859, 2020). "Other studies, including a nested case-control study of Japanese-American men and a retrospective cohort study of European aged 60 years or over, investigated the association of lifestyle and genetic risk factors (ε4 allele of the apolipoprotein E gene) with the incidence of dementia." (PMID 32867702, 2020). "Here we found that Iba1 microglia density was associated with increasing tau pathology in APOE ε4 carriers, suggesting that an association with dementia may be due to APOE ε4 carrier status." (PMID 32076055, 2020). "Therefore, to the best of our knowledge, this is the first study to demonstrate that APOE ε4 allele was an independent risk factor for incident dementia in CADASIL." (PMID 33328970, 2020). "Additionally, the Framingham Heart Study reported that participants who had more cardiovascular risk factors or carried at least one Apolipoprotein E (APOE) ɛ4 allele had a greater than two-fold risk of developing dementia." (PMID 33352859, 2020). "Given the distinct metabolic roles of these lipoproteins, the association of apoE with dementia might depend on the lipoprotein where it is located." (PMID 32648923, 2020). "Likewise, although dementia is likely the major cause of death among seniors of APOE*ε4 carriers, APOE*ε4 also mediates a detrimental effect on survival in non-demented aged people." (PMID 33148290, 2020). "The risk attributable to APOE*ε4 for depression is less clear and may be because of confounding of the relationship between dementia and depression." (PMID 32381152, 2020). "Turning to the genetic level, we took a known genetic risk factor for dementia in DS in adulthood, the APOE genotype, and assessed whether it explained any of the variation we observed in early vocabulary development." (PMID 32653761, 2020). "Hence, it can be of great importance to perform long-term investigations on how the APOE level and cerebrospinal fluid changes in the early-, mid- and late-life are connected with a higher/lower risk for development of dementia." (PMID 33066592, 2020). "The risk of dementia has been considered to be affected by environmental risk factors (e.g., hypertension, smoking, diabetes, physical inactivity) and genetic risk factors (e.g., APOE genotypes)." (PMID 33129280, 2020). "Additionally, the interaction of SCD with other risk factors for dementia due to AD, such as age and the Apolipoprotein E (ApoE) ɛ4 status, has also been described." (PMID 32962744, 2020).
dementia (continued). "Future research that assesses more established risk factors for dementia (e.g., APOE genotype, cardiovascular function, depression, anxiety, hearing loss) in addition to other potential causes of SCD (e.g., medication use, physical health) are needed to clarify the role of RNT in this risk profile." (PMID 33036587, 2020). "When focusing on the detail of the hazard ratio sizes observed in the additive interactions between NPS and APOE ɛ4, it is observed that synergistic effects have an incremental risk of dementia conversion ranging from 30% to more than 100% compared to nonaffected MCI peers." (PMID 33208795, 2020). "Finally, it is well known that APOE ε4 has been identified as a risk factor for AD, while in this study, the conversion rates are calculated for all forms of dementia." (PMID 33208795, 2020). "On the other hand, it has been shown that education, job complexity, leisure activities, and social network may attenuate the genetic risk of dementia due to APOE ɛ4, possibly by enhancing cognitive reserve and reducing stress levels." (PMID 32081835, 2020). "Promoter polymorphisms may increase the dementia risk through the APOE4 pathway, with expression levels of APOE4 determined by APOE promoter polymorphisms." (PMID 32694990, 2020). "In particular, the APOE ε4 allele is closely associated with elevated levels of total cholesterol and low-density lipoprotein cholesterol with increased risk of dementia and cognitive impairment." (PMID 32581766, 2020). "To determine whether Δtau314 associates with dementia independently of APOE ε4, we compared Δtau314 in demented (LDB) and cognitively intact (PD) APOE ε4 non-carriers." (PMID 31362787, 2019). "In addition, participants carrying an APOE ε4 allele were at increased risk of incident delirium, likely contributing to the increased risk of dementia observed after an episode of delirium." (PMID 30770424, 2019). "Delirium and dementia share a common risk factor in APOE genotype, which may contribute to the high rates of incident dementia observed after an episode of delirium." (PMID 30770424, 2019). "With the availability of longitudinal health outcomes, future studies may also explore the role of the dementia-associated APOE ε4 allele on hippocampal volume across age." (PMID 31254939, 2019). "This scale assigns scores to participants on their characteristics, taking into account some of the most important risk factors for dementia (age, education, sex, systolic blood pressure, body mass index (BMI), total cholesterol, physical activity, and APOE status)." (PMID 30678723, 2019). "However, the primary goal of this Japanese study was to examine the effect of the APOE allele on dementia onset, which had a very different focus than that of our study." (PMID 30753205, 2019). "Later than expected intergenerational difference in AAO was associated with parental history of early-onset dementia (β = 21.30 [95% CI, 15.01-27.59]), presence of 1 APOE ε4 allele (β = 5.00 [95% CI, 2.11-7.88]), and history of hypertension (β = 3.81 [95% CI, 0.88-6.74])." (PMID 31617930, 2019). "Second, some studies suggest that the associations of alcohol consumption with dementia risk may vary by the absence or presence of the apolipoprotein E ε4 (APOE E4) allele, but reports are conflicting." (PMID 31560382, 2019). "Our results on the differential role of the APOE ε4 allele in BMI in younger and older individuals contribute to better understanding of genetic architecture underlying differential role of elevated mid‐ and late‐life BMI in risks of AD and dementia." (PMID 30462377, 2019). "Although the sample size was too small to ensure complete reliability of the logistic regression analysis, a lower prevalence of Bacteroides and a higher prevalence of ‘other’ bacteria were associated with higher odds ratios than the traditional dementia biomarkers ApoE ε4, SLI and high VSRAD score." (PMID 30700769, 2019).